INS (insulin)
Diseases named in the same sentence as INS in open-access papers (continued):
Sharing a sentence is not in itself a finding about the gene and the disease.
Insulin resistance (continued). "In addition, CEACAM1 controls insulin clearance to protect against insulin resistance, obesity, WAT-associated inflammation, hepatosteatosis (NAFLD), NASH, fibrosis and cardiovascular disease, as bolstered by observations in mice with global deletion of CEACAM1 expression." (PMID 30314283, 2018). "The overexpression of RBP4 in wild-type mice causes insulin resistance while genetic depletion of Rbp4 improves insulin sensitivity, suggesting that the depleting level of RBP4 could be helpful in the treatment of T2DM, and levels of RBP4 could serve as a biomarker for T2DM." (PMID 29740397, 2018). "Furthermore, caffeine consumption in some levels may result in improved insulin sensitivity, which can play an important role in energy regulation and expenditure, and obesity is always associated with insulin resistance and type 2 diabetes." (PMID 30103464, 2018). "Insulin resistance linked to obesity or type 2 diabetes is associated with decreased cellular glucose uptake in the adipose and muscle tissues and increased glucose output from the liver, which may be caused in part by impaired proximal insulin signaling." (PMID 30521580, 2018). "Current therapeutic strategies for attenuating insulin resistance aim to encourage lifestyle modifications (e.g., diet, exercise, weight loss) as a first-line offense prior to the administration of pharmacological agents (e.g., insulin-sensitizing drugs) to patients." (PMID 29601521, 2018). "Insulin differentially regulates adipose tissue and skeletal muscle sirtuin 1 expression in the short-term and circulating free fatty acids elevation negates these effects, which may be associated with lipid-induced insulin resistance." (PMID 29417372, 2018). "Furthermore, insulin resistance is observed in the neuronal cells of patients with Alzheimer’s disease (AD), which suggests that insulin resistance may cause neuronal cell dysfunction and lead to cognitive dysfunction and dementia." (PMID 29330465, 2018). "Indeed, insulin resistance is associated with increased basal lipolytic rate and the generation of FFAs, while partial inhibition of adipose tissue lipolysis can improve glucose metabolism and insulin sensitivity." (PMID 29853530, 2018). "This study demonstrated that insulin resistance and sensitivity markers were independent predictors of cIMT in overweight and obese boys, but not in girls, highlighting the importance of chronically elevated insulin levels for predisposing these boys to alterations in their vascular structure." (PMID 30470212, 2018). "Furthermore, proteomic analysis of the adipose tissue secretome has recently identified several novel adipokines including vaspin, chemerin and pref-1 that are associated with obesity and insulin resistance in humans and functionally impact on insulin signalling pathways." (PMID 29760587, 2018). "Therefore, improved insulin metabolism by vitamin D supplementation may decrease the risk of metabolic complications subsequent to insulin resistance in these patients." (PMID 30286768, 2018). "Leptin resistance may cause an increase in insulin requirement and insulin resistance." (PMID 30050584, 2018). "Thus, our data do not support that the proposed mechanisms in ‘the glucose fatty-acid cycle’ hypothesis cause reduced insulin-stimulated glucose uptake during prolonged fasting or insulin resistance associated with obesity." (PMID 30183740, 2018). "However, whether serum UA is associated with insulin resistance and insulin secretion, and the effect of gender on it in the case of the existed association, both remain undefined." (PMID 29568712, 2018). "Thus, in the same way that increased insulin levels may be induced by the presence of insulin resistance, an ASP resistance may cause an increased ASP precursor levels (C3)." (PMID 30454064, 2018). "Thus, periodontitis may enhance insulin resistance and impair insulin secretion leading to increased morbidity associated with diabetic complications." (PMID 29621153, 2018).
Insulin resistance (continued). "Thus, it is still unclear whether low MCRI is a consequence of slightly impaired insulin sensitivity or a cause of insulin resistance and adiposity." (PMID 28469173, 2017). "Thus, central nervous insulin administration regimens focusing on the sleep period may exert beneficial effects on metabolic health and might even help prevent or treat the brain insulin resistance associated with metabolic disorders." (PMID 28228715, 2017). "In addition to the association between insulin resistance and albuminuria, hyperinsulinaemia per se is related to albuminuria in type 2 diabetes and in type 1 diabetes, where nephropathy is associated with higher therapeutic doses of insulin." (PMID 28852804, 2017). "Additionally, hyperosmotic stress might be associated with insulin resistance in diabetes type 2 by inhibiting insulin-mediated signal transduction in adipocytes." (PMID 28046026, 2017). "Melatonin inhibits the release of insulin from pancreatic beta cells, although conflicting research exists with the Nurses’ Health Study finding low melatonin associated with increased risk of type 2 diabetes, potentially medicated through increased insulin resistance." (PMID 28775759, 2017). "Since, despite a normal BMI, a high body fat mass leads to increased levels of pro inflammatory cytokines, increased serum insulin concentrations, insulin resistance, and decreased insulin sensitivity, obese women with normal weight may be at risk for metabolic disorders and metabolic syndrome." (PMID 29299442, 2017). "In the case of type-1 diabetes (T1D), the underlying insulin deficiency is a result of pancreatic β-cells destruction by autoimmune-mediated response, while type-2 diabetes (T2D) is mainly caused by insulin resistance, although impaired insulin secretion and β-cell death may also be evident." (PMID 29023424, 2017). "Insulin resistance resulting from obesity is associated with a particular milieu of circulating factors in the plasma, any of which could signal β-cells to fail to adapt to increased insulin demand." (PMID 28168202, 2017). "Insulin has been shown to be less effective in improving glucose tolerance in an inflamed environment due to insulin resistance caused by inflammatory cytokines; however, the role of adipose tissue inflammation as a driver of insulin resistance is still debated." (PMID 28660193, 2017). "Hypothesis: Palmitate causes insulin resistance (IR) in insulin target tissue." (PMID 29362600, 2017). "This could be a sign of increased insulin sensitivity because insulin resistance is associated with high levels of circulating fatty acids, which can inhibit the insulin-signaling pathway, which was observed in the lean moderate-protein versus lean high-protein-fed animals." (PMID 28594375, 2017). "However, metformin therapy decreases levels of IGF-1, improves insulin resistance in peripheral tissues, and alleviates the circulating insulin levels, which, in turn, may result in reduced risk of cancer." (PMID 27903961, 2017). "It was found that decreased intracellular enzymatic activity, attributed to magnesium deficiency, might favour insulin resistance, while extracellular magnesium is also needed to prevent a rise in intracellular calcium concentration, which impairs insulin signalling as well." (PMID 28978343, 2017). "However, serum insulin levels and the homeostasis model assessment of insulin resistance, which are implicated in the main pathogenesis of NAFLD, might invariably influence all the LSM methods." (PMID 29176844, 2017). "However, the NMR-derived LP-IR measurement is strongly associated with both the homeostasis model assessment of insulin resistance (r = 0.51) hereby being reflective of hepatic IR, and with glucose disposal rates (r = −0.53) hereby reflecting peripheral insulin sensitivity." (PMID 28230201, 2017).
Insulin resistance (continued). "As the ß-estimates in our study and the results from the random forest analysis also point towards a stronger association of leptin to the metabolome compared to insulin to the metabolome, this finding of ours might be explained by early stages of insulin resistance or fatty liver in some children." (PMID 28817652, 2017). "We hypothesize that reduced insulin sensitivity may play a vital role in the prolonged QTc interval in type 2 diabetes, although previous studies have implicated a weak association of insulin resistance with an increased QTc interval in a relatively small sample size of type 2 diabetes patients." (PMID 28912840, 2017). "These unsaturated PCs could activate PC-Transfer Protein complex formation, involved in decreasing insulin signaling, indicating a potential mechanistic role of PCs in the development of insulin resistance associated with high concentration of total blood cholesterol in plasma." (PMID 28278231, 2017). "Importantly, we found that BCAA levels are associated with the degree of hepatic and peripheral insulin resistance; in particular, high concentrations of BCAAs were negatively correlated to the ability of insulin to suppress hepatic glucose production as well as to the glucose disposal rate." (PMID 28640216, 2017). "Finally, we analysed whether testosterone levels were associated with fasting insulin and insulin resistance, as measured by the homoeostatic model assessment (HOMA IR)." (PMID 28546543, 2017). "The purpose of this study was to examine associations between incident CRC and blood glucose; plasma insulin; and the homeostasis model assessment for insulin resistance (HOMA2-IR), respectively, and to determine whether these associations were dependent on sex and cancer site." (PMID 29233100, 2017). "However, it has been shown that high levels of fasting insulin, an index of insulin resistance, were positively associated with the low-to-high frequency (LF/HF) ratio of the heart rate variability (HRV)—an index of the sympathovagal balance at the heart level." (PMID 27147943, 2016). "Although insulin resistance is a feature of normal pregnancy, the male placenta may cause the mother to become relatively more insulin resistant and in association with other factors, this may increase the risk of GDM and macrosomia in male bearing pregnancies." (PMID 27398996, 2016). "Insulin resistance and hyperinsulinemia are clinically important since the effects of insulin have been shown in the formation of atherosclerotic plaques, and, hence, increased risk of hypertension and atherosclerosis has been attributed to insulin resistance in postmenopausal women." (PMID 27275336, 2016). "Therefore, the aim of our present study is to determine the effect of Gelam honey extract and quercetin on the JNK and IKK-β inflammatory pathways and IRS-1 serine phosphorylation which causes insulin resistance and the Akt activated insulin signaling pathway, which improves insulin resistance." (PMID 27034691, 2016). "Additionally, insulin levels and insulin resistance showed associations with the African component." (PMID 27350247, 2016). "In addition to reflecting known signaling events implicated in obesity, such as aberrant insulin signaling and associated insulin resistance, the snapshot of the adipocyte phosphoproteome points to intricate rewiring of metabolic network in a phosphorylation-dependent manner." (PMID 27180971, 2016). "Therefore, it was proposed that the reduced insulin sensitivity during sodium restriction could contribute to hyperinsulinism, which can in turn induce insulin resistance and is associated with cardiovascular disease and type 2 diabetes." (PMID 28066329, 2016). "Furthermore, according to the hypothesis developed by Barker, scarce intrauterine growth would cause a deterioration in insulin resistance, and in turn, elevated levels of insulin have been associated with increased blood pressure also in children." (PMID 27423331, 2016).
Insulin resistance (continued). "Moreover, C10‐OH/C8‐DC and total hydroxyl‐/dicarboxyl‐acylcarnitine levels tended to be negatively associated with the serum insulin level, and the total hydroxyl‐/dicarboxyl‐acylcarnitine level additionally tended to be negatively associated with the hepatic insulin resistance index." (PMID 27694528, 2016). "In addition, treatment of type 2 diabetes associated with insulin resistance by Origanum and normalization of blood glucose levels may be results from restoration of normal insulin sensitivity." (PMID 28228803, 2016). "The positive association between insulin and prepregnancy BMI (r = +0.38), gestational BMI (r = +0.24), and hyperglycemic disorders (r = +0.26) met the metabolic syndrome diagnosis criteria, whose physiopathologic basis is the association between obesity and insulin resistance." (PMID 27651836, 2016). "Thus, it has been suggested that insulin resistance may be caused in part by the disruption of caveolae/lipid rafts that leads to altered localization of insulin receptor and disassembly of insulin signaling molecules." (PMID 28030645, 2016). "Furthermore, glycine and other amino acids might directly cause insulin resistance by disrupting insulin signaling." (PMID 27383746, 2016). "Moreover, we found that C10‐OH/C8‐DC and total hydroxyl‐/dicarboxyl‐acylcarnitine levels tended to be negatively associated with the serum insulin level, and the total hydroxyl‐/dicarboxyl‐acylcarnitine level additionally tended to be negatively associated with the hepatic insulin resistance index." (PMID 27694528, 2016). "The possibility that clinical management of insulin sensitivity is considered a therapeutic target in the treatment of mothers with this disease could result in reversing along with insulin resistance, the GDM-associated alterations in ERS, angiogenesis and lipids metabolism." (PMID 27065887, 2016). "Furthermore, we investigated the effect of Gelam honey extract and quercetin on the stress activated NF-κB and MAPK pathways and IRS-1 serine phosphorylation causing insulin resistance and the Akt activated insulin signaling pathway, causing increase in insulin content." (PMID 27034691, 2016). "Furthermore, there is a highly significant relationship between obesity, plasma insulin concentration, and increased BP, although the mechanisms by which insulin resistance, hyperinsulinemia, or both increase the risk of developing cardiovascular disease are not well defined." (PMID 26880072, 2016). "In addition, insulin has important cardiovascular, renal, and neural functions, which may explain why insulin resistance is a risk factor for microvascular complications such as retinopathy, nephropathy, hypertension, and CVD." (PMID 27478531, 2016). "The adiponectin, on the other hand, induces insulin-sensitizing effects and its enhanced expression has been shown to improve insulin sensitivity and glucose tolerance while its deficiency could induce insulin resistance." (PMID 27775654, 2016). "Since oxidative stress is associated with chronic hyperglycemia-induced insulin resistance and a decline in insulin biosynthesis and secretion, we are tempted to speculate that the oxidative stress resistance putatively conferred by FGF21 contributes to the beneficial metabolic actions of FGF21." (PMID 26089880, 2015). "In addition, associated insulin resistance and high circulating insulin may further promote tumor growth via insulin like growth factor (IGF) signaling pathways." (PMID 26015297, 2015). "In addition, suppressor of cytokine signaling (SOCS) proteins, which are feedback inhibitors of pathways induced by cytokines, may indirectly downregulate insulin signaling, resulting in reduced glucose transport into cells, the hallmark of insulin resistance." (PMID 26539824, 2015).
Insulin resistance (continued). "Therefore, decreased myogenesis coupled with a decrease in key insulin signaling molecules in PCUN singleton fetuses may result in the increased risk of insulin resistance and impaired glucose uptake which occurs in response to PCUN in later life." (PMID 26265755, 2015). "It has been postulated that with increased abdominal adiposity there is greater lipolytic activity leading to an increase in free fatty acids (FFA), which may inhibit insulin secretion and insulin-stimulated glucose uptake and thus increase the risk for insulin resistance and T2D." (PMID 26321962, 2015). "Despite extensive observations on insulin-resistant and sensitive obesity, information is scant regarding whether the association between childhood adiposity and MetS in later life is dependent on insulin resistance." (PMID 26640243, 2015). "In contrast to the thiazolidinediones, antidiabetic drugs that act by binding to and activating PPAR-γ, which improve insulin sensitivity by mechanisms which may involve increase in adiponectin, treatment with niacin often causes increased glucose levels and insulin resistance." (PMID 26063948, 2015). "Thus, our aim was to investigate whether insulin resistance, elevated concentrations of insulin or glucose were associated with impaired episodic and/or semantic memory in a non-diabetic and non-demented population." (PMID 25798199, 2015). "Additionally, recent evidence indicated that higher intake fast food and greater access to the fast foods may lead to higher insulin levels and risk of insulin resistance." (PMID 26447855, 2015). "Furthermore, it has been reported that HbA1c had a strong correlation with elevated FPG levels, which are mainly caused by insulin resistance, while GA was closely related to higher postprandial glucose levels, which are attributed to reduced insulin secretion." (PMID 26099223, 2015). "This study demonstrated a decrease in fat cell volume with adipocytes losing their lipid content leading to the hypothesis that adipocytes chronically exposed to high local insulin levels could develop insulin resistance resulting in an increase in the lipolytic process causing lipoatrophy." (PMID 28702229, 2015). "Therefore, an elevated serum level of insulin can theoretically cause breast cancer via the crosstalk between insulin and insulin receptor and/or insulin-like growth factor receptors, especially in the presence of insulin resistance." (PMID 26171401, 2015). "Indeed, such perturbed lipid metabolism in insulin-resistant states is typically manifested as a mixed dyslipidemia, and may indeed be causal in the development of insulin resistance." (PMID 26486974, 2015). "The “thrifty phenotype hypothesis”, which postulates that fetal programming for adaptation to an adverse intrauterine environment results in lower insulin sensitivity in utero, is one of the hypotheses to explain the association between low birth weight and insulin resistance in later life." (PMID 29546136, 2015). "Thus, he may have been “primed” by underlying insulin resistance and baseline chronic elevation of his insulin secretion machinery which together exacerbated sulfonylurea-induced hypoglycemia." (PMID 26664768, 2015). "Metabolites related to triglyceride-fatty acid interconversion such as fatty-acyl CoA, diacylglycerol, and ceramides have been shown to disrupt insulin signaling and have therefore been hypothesized as the causative agents of insulin resistance in the setting of elevated ectopic lipid." (PMID 26236747, 2015). "Furthermore, it has been shown that high levels of fasting insulin, an index of insulin resistance, were positively associated with the low-to-high frequency (LF/HF) ratio of the heart rate variability (HRV)—an index of the sympathovagal balance at the heart level." (PMID 26379553, 2015).